ZEB1 (zinc finger E-box binding homeobox 1)
Diseases named in the same sentence as ZEB1 in open-access papers (continued):
Sharing a sentence is not in itself a finding about the gene and the disease.
breast carcinoma (continued). "The results of CCK-8, wound-healing and transwell assays indicated that ectopic Zeb1 expression promoted breast cancer cell viability and migration; however, treatment with the LDHA inhibitor OXM significantly weakened these effects." (PMID 35246504, 2022). "We also performed Zeb1 gain- and loss-of-function assays in MDA-MB-231 and SUM-159 human breast cancer cells." (PMID 35246504, 2022). "PTBP3 is upregulated in breast cancer and regulates ZEB1 mRNA stability to promote epithelial-mesenchymal transition in BRCA." (PMID 36203873, 2022). "Our study displayed that ubiquitination of ZEB1 is significantly enhanced in shRNA-SENP1 breast cancer transfected group, compared with control group." (PMID 35342335, 2022). "OGN can reverse EMT through the PI3K/Akt/mTOR pathway in breast cancer, and reduce the expression of ZEB-1 through the EGFR/Akt signaling pathway in colon cancer to inhibit EMT." (PMID 35513835, 2022). "Research indicates that ZEB1 mediates CDH1 downregulation in basal cell-like breast cancer and recruits DNMT1 to the CDH1 promoter to maintain the methylation status of the promoter." (PMID 36076302, 2022). "We show that ERα protein levels in our luminal breast cancer cells are still relatively high 5 weeks after the induction of ZEB1 expression and that cells maintain epithelial features." (PMID 35440541, 2022). "ZEB1 as a direct transcriptional repressor of E-cadherin by physically binding to the proximal promoter of E-cadherin in breast cancers." (PMID 36118870, 2022). "Endothelial JAG1 activates the Notch1 receptor on breast cancer cells to induce Zinc finger E-box-binding homeobox 1 (ZEB1) expression, which subsequently leads to the expression of stem cell markers." (PMID 35805056, 2022). "In another study, GPC3 re-expression in aggressive breast cancer cells returned mesenchymal-like breast cancer cells to an epithelial phenotype as shown by the suppression of Snail, ZEB1, vimentin, and increased expression of E-cadherin." (PMID 36358747, 2022). "In vitro studies suggest that ZEB1 not only initiates invasion, but that conditioned medium from these invasive ERα– breast cancer cells promotes the maturation of osteoclasts while repressing osteoblast differentiation." (PMID 35440541, 2022). "We used the GOBO database and extracted the data for ERα+ breast cancer patients in relation to ZEB1 and CD151 expression levels." (PMID 35440541, 2022). "In the breast cancer TCGA datasets, we found that the expression of ZEB1 was positively correlated with FTO." (PMID 36302751, 2022). "Here we show that, shortly after induction of EMT and while cells are still epithelial, ZEB1 modulates ERα-mediated transcription induced by estrogen or cAMP signaling in breast cancer cells." (PMID 35440541, 2022). "Mechanistically, breast cancer cells with ectopic Zeb1 expression produce lactate in the acidic tumor milieu to induce the alternatively activated (M2) macrophage phenotype through stimulation of the PKA/CREB signaling pathway." (PMID 35246504, 2022). "The results revealed that depletion of Zeb1 inhibited the expression and activity of HK2, PFKP and PKM2; however, ectopic Zeb1 expression had the opposite effect to enhance the glycolytic phenotypes in breast cancer cells." (PMID 35246504, 2022). "Together, these findings indicate that ZNF384 contributes to breast cancer progression by transactivating ZEB1 expression." (PMID 36100877, 2022). "The suppression of ZEB1 in MDA-MB-231 human breast cancer cells results in the overexpression of around 200 genes and the downregulation of approximately 30 genes, the majority of which are determinants of epithelial differentiation and cell–cell adhesion." (PMID 35409206, 2022). "In summary, our findings demonstrated that breast cancer cells exhibit aberrant glycolytic metabolism mediated through a Zeb1-dependent mechanism that confers aggressive and immunosuppressive properties to tumors." (PMID 35246504, 2022).
breast carcinoma (continued). "Among the regulators of the EMT process, ZEB1 has been proved to be a critical regulator for PD-L1 expression in lung cancer, breast cancer, gastric cancer, and diffuse large B cell lymphoma." (PMID 35242187, 2022). "miR-200b/200a/429 suppressed the metastatic potential of breast cancer cells by decreasing the expression of ZEB1." (PMID 35682560, 2022). "In breast cancer, ZEB1 represses the transcription of the CDH1 gene, by targeting the E-box of the gene promoter." (PMID 35454770, 2022). "As a powerful EMT-related transcription factor, ZEB1 expression is found to be highly expressed in many malignancies, such as lung cancer, breast cancer and pancreatic cancer." (PMID 35468721, 2022). "ZEB1 is overexpressed in breast cancer, glioma and pancreatic cancer, induces epithelial-mesenchymal transition (EMT) and promotes tumor invasion." (PMID 36085146, 2022). "Our results also demonstrated that DNMT1 was expressed at high levels in breast cancer patients with high ZEB1 expression." (PMID 36273188, 2022). "Compared to luminal breast cancer subtypes, ZEB1 is highly expressed in triple-negative breast cancers, which express neither ERα nor progesterone receptor (PR), which is encoded by an ERα target gene." (PMID 35440541, 2022). "This study reveals that ZEB1 is upregulated by autophosphorylation as well as by ATM hyperactivation in radioresistant breast cancer cells." (PMID 35454770, 2022). "The expression level of ZEB1 by induction ATM activation occurs in chemoresistance in human breast cancer." (PMID 36499447, 2022). "Rb dephosphorylation regulates EMT by inhibiting the ZEB1 transcriptional activity in breast cancer." (PMID 36499447, 2022). "A recent study in human breast cancer found that CSC plasticity relied on ZEB1, a key regulator of the EMT." (PMID 35646083, 2022). "Their study shows that metaplastic carcinomas of the breast have histological evidence and express biological markers of an epithelial to mesenchymal transition characterized by progressive overexpression of ZEB1 and downregulation of E-cadherin." (PMID 36092916, 2022). "As in mammary and breast cancer cells, the ZEB1 promoter is regulated by Fra-1, and ZEB1 is a Fra-1 effector in melanoma cells." (PMID 35326630, 2022). "As an miRNA sponge, circDNMT1 maintains the highly proliferative state of breast cancer by regulating the miR-485-3p/ZEB1 axis." (PMID 35712504, 2022). "We used the Gene expression-based Outcome for Breast cancer Online (GOBO) tool to correlate ZEB1 expression with outcome in ERα+ and ERα– breast cancer patients." (PMID 35440541, 2022). "Cordycepin inhibited the expression of N-cadherin, snail, and ZEB1 in breast cancer and enhanced the expression of E-cadherin." (PMID 36142286, 2022). "Based on our findings, we proposed that Zeb1 directly promotes the expression of key glycolytic genes that facilitate the Warburg effect and aggressiveness of breast cancer in vitro and in vivo." (PMID 35246504, 2022). "In MDA-MB-231 breast cancer cells, high ZEB1 expression increases the synthesis of vascular endothelial growth factor A, thereby inducing tumorigenesis and angiogenesis." (PMID 35454770, 2022). "TGF-β-induced EMT-related transcription factor ZEB1 decreases cholesterol in breast cancer cells by forming a complex with C-terminal-binding protein, and the ZEB1-C-terminal-binding protein complex binds to the SREBF2 promoter and inhibits its activity." (PMID 36115986, 2022). "MiR-429 is probably involved in regulating the bone metastasis of breast cancer cells by targeting ZEB1 and CRKL." (PMID 35468721, 2022). "Our data indicate that ZEB1 modulates gene signatures related to bone development and abnormal phenotypes in ERα+ breast cancer cells." (PMID 35440541, 2022).
breast carcinoma (continued). "In breast cancer, ZEB1 promotes inflammation in the tumor microenvironment by regulating the secretion of the proinflammatory cytokines interleukin 6 (IL-6) and IL-8 and subsequently inducing the growth of fibroblasts and myeloid-derived suppressor cells." (PMID 35454770, 2022). "Recent evidence has suggested that aberrant expression of Zeb1, which is mostly found at the invasive front of carcinomas, promotes the malignant progression of breast cancer and other cancer types." (PMID 35246504, 2022). "In brief, Linc00894 was found to competitively bind to miR-429 and regulate the expression of transcriptional factor zinc finger E-box binding homeobox 1 (ZEB1) which leads to breast cancer progression." (PMID 36139687, 2022). "For instance, TTN-AS1 promoted proliferation and invasion of breast cancer cells by interaction with the miR-139-5p/ZEB1 axis." (PMID 36119544, 2022). "We discovered that ZEB1 activates DNMT1 expression in breast cancer cells by recruiting P300 binding to the DNMT1 promoter and increasing its acetylation." (PMID 36273188, 2022). "In breast cancer cells, zinc finger E-box binding homeobox 1 (ZEB1) activated VEGFA transcription through enhancing SP1 recruitment to VEGFA promoter." (PMID 36467048, 2022). "For example, evidence shows that SETD8 induces the EMT and enhances metastasis in prostate and breast cancers by cooperating with Zinc finger E-box-binding homeobox 1 (ZEB1), a transcriptional repressor, and the transcriptional factor TWIST, respectively." (PMID 35246238, 2022). "In order to scrutinize this evidence deeper and based on the result that the mesenchymal breast cancer stemness markers ZEB1 and CD44 best correlated with 3D mammosphere growth, we adopted an alternative protocol." (PMID 35348275, 2022). "The results indicate that SENP1 downregulation blocks epithelial-mesenchymal transition (EMT) process and thus inhibits breast cancer cell invasion and metastasis, which is mediated via ZEB1 expression." (PMID 35342335, 2022). "Mechanistically, the oncogenic role of HOTAIR in breast cancer was mediated by the sponging of miR-601 and subsequently regulated ZEB1 expression." (PMID 36613528, 2022). "Previous research indicated that ZEB1 was the critical regulator for PD-L1 expression among a panel of transcription factors in the EMT process in breast cancer." (PMID 35242187, 2022). "High ZEB1 expression was also positively correlated with high DNMT1 expression in our detected TMA breast cancer tissues." (PMID 36273188, 2022). "In basal-like breast cancer, ZEB1 recruits DNMT1 to the promoter for CDH1, acting as an epigenetic modulator by maintaining methylation status and downregulate the presence of e-cadherin." (PMID 36230521, 2022). "We also performed these experiments in SUM-159 cells and obtained similar results, collectively revealing that aerobic glycolysis contributes to tumor progression and chemoresistance in breast cancer cells with ectopic Zeb1 expression." (PMID 35246504, 2022). "ZNF384 transactivated ZEB1 expression and induced an epithelial and mesenchymal-like phenotype, resulting in breast cancer metastasis." (PMID 36100877, 2022). "Specific to breast cancer, dedifferentiation is proposed to be due to ZEB1-based driving of EMT events, which is also required for conversion of non-CSC to CSC and for the maintenance of CSC-like activity." (PMID 35597788, 2022). "ZEB1, a regulator of EMT, induced autophagy to cause anti-cancer drug resistance in breast cancer cells." (PMID 35682560, 2022). "Connexins linked to N-cadherin, vimentin, Snail, and Zeb1 modulate CSC and EMT properties in breast cancer cells." (PMID 35464064, 2022). "By analyzing the ZEB1-ERα interdependent transcriptional activities, we reveal new mechanisms by which ZEB1 drives tumor progression and invasion of ERα+ breast cancer cells." (PMID 35440541, 2022).
breast carcinoma (continued). "Downregulation of miR-200 causes the induction of EMT by the transcription factors ZEB1 and ZEB2, leading to the dissemination of breast cancer cells." (PMID 35884446, 2022). "Evidence has shown that Snail induces metastasis in breast cancer, while ZEB1 tends to induce pancreatic cancer metastasis." (PMID 35805066, 2022). "In particular, USP51 deubiquitinates ZEB1’s N-terminal region and minces metastasis and therapy resistance in breast cancer." (PMID 36499447, 2022). "This study aimed to investigate the effect of Zinc Finger E-box Binding Homeobox 1 (ZEB1) regulation by Micro Ribonucleic acid (miR)-448 on Breast Cancer (BC) cells and their sensitivity to chemotherapy." (PMID 35905576, 2022). "Our results are supported by findings described in breast cancer cells, where ZEB1 expression plays a pivotal role in the maintenance of stem-like features, immune evasion, epigenetic reprogramming, and aberrant cellular polarity." (PMID 35804889, 2022). "Similarly, aberrant expression of TG2 in breast cancer (BC) was associated with loss of E-cadherin and upregulation of the transcriptional repressors, Snail1, Zeb1, Zeb2 and Twist1." (PMID 35681474, 2022). "VEGF-A as a downstream factor of Zeb1 enhances breast cancer cells’ aggressiveness through sustaining stemness." (PMID 33681207, 2021). "A study indicated that B-cell CLL/lymphoma 6 (BCL6) promotes EMT via enhancing the ZEB1-mediated transcriptional repression of E-cadherin in breast cancer cells." (PMID 34217266, 2021). "Activated human T cells are involved in the synthesis of IL-6, TNFα, and TGFβ which induce the expression of mesenchymal proteins such as fibronectin, vimentin, and Zeb1 in inflammatory breast cancer cells." (PMID 34220337, 2021). "Some established oncogenes are also direct targets of miR-655 in other types of cancers, such as Prrx1 in breast cancer, ZEB1 and TGFBR2 in ESCC, ADAM10 in hepatocellular carcinoma, and PAX6 in retinoblastoma." (PMID 33643926, 2021). "Circular RNA hsa_circ_001783 sponges miR-200c-3p in breast cancer, which leads to the upregulation of miR-200c-3p target genes ZEB1, ZEB2, and ETS1." (PMID 34439151, 2021). "More recently, tissue array analysis of 448 cancer samples from multiple organs revealed positive correlations between Zeb1 and IL-6 protein levels in various cancer types, including liver, colon and breast cancer." (PMID 34361105, 2021). "The detection of shared gene sets, co-regulated by ZEB1/YAP in breast cancers, suggests the existence of a coregulatory network that supports malignant cancer progression and therapy resistance." (PMID 34439395, 2021). "Transforming growth factor-β (TGF-β) induces ZEB1 and promotes bone-specific metastasis of breast carcinomas." (PMID 35008751, 2021). "On the contrary, in our epithelial breast cancer cell system (MCF-7) ectopic expression of Zeb1 conferred a partially mesenchymal phenotype to the cells, emphasizing the significance of Zeb1 interactions observed." (PMID 34074001, 2021). "They observed in breast cancer cell lines that tumor growth factor beta (TGF-β)-induced activation of Zeb1 was dependent on promoter methylation status." (PMID 34072345, 2021). "Forced expression of TP53BP1 in breast cancer cell lines led to upregulation of miR-200b and miR-429, downregulation of ZEB1, and an epithelial-like phenotype, while silencing of TP53BP1 had the opposite effects." (PMID 34884985, 2021). "ZEB1 has also been reported to transform non-invasive breast cancer cells into highly malignant cancer stem cells (CSCs)." (PMID 34462429, 2021). "The same study also confirmed that oleuropein significantly reduces the expression of an EMT-inducer transcription factor zinc finger E-box binding homeobox 1 (ZEB1) in breast cancer cells." (PMID 34578851, 2021). "It is reported that DDB2 transcriptional regulates IκBα and SOD2 in breast cancer cells, and Snail, Zeb1 and VEGF in colon cancer." (PMID 33557942, 2021).
breast carcinoma (continued). "ΔNp63 has also been linked to selective regulation of EMT factors in breast cancer cells, as upregulation of SNAI2 lead to increased migration while miR-205 mediated inhibition of ZEB1 and ZEB2 resulted in EMT suppression." (PMID 34964086, 2021). "CHEK1 is a serine–threonine protein kinase that regulates EMT through ZEB1-mediated signaling in breast cancer cells." (PMID 34455105, 2021). "A previous study described how LPAR1 plays a key role in tissue fibrosis and carcinogenesis 57 and modulates metastasis in basal breast cancer by activating the LPA1/ZEB1/miR-21 pathway." (PMID 34104083, 2021). "Activated HIF1α or HIF2α directly or indirectly regulate SNAI1, TWIST1 and ZEB1 expression which fosters stemness and metastasis formation in bladder, ovarian, gastric and breast cancer." (PMID 34459003, 2021). "In an experiment conducted by Mahsa and colleagues using MCF-7 breast cancer cells, an inverse correlation was found between miR-30c and Zeb1." (PMID 33414456, 2021). "Weinberg and others have shown that Slug and Snail both bind and regulate ZEB1 expression; however, the expression of SLUG is associated with breast cancers that arise from cells containing normal mammary epithelial stem cells in the basal compartment." (PMID 34579762, 2021). "In pathological conditions such as breast cancer, this balance is possibly disturbed due to high replicative stress, except in ZEB1-expressing cells, as formerly demonstrated." (PMID 34458275, 2021). "SNHG3 promotes migration, invasion, and epithelial-mesenchymal transition of breast cancer cells through the miR-186-5p/ZEB1 axis." (PMID 34277410, 2021). "We previously found that ZEB1 is highly expressed in breast cancers and confers basal breast cancer resistant to conventional chemotherapy and neoadjuvant therapy." (PMID 34462429, 2021). "Overexpression of SNAI1, TWIST1, and ZEB1 in breast cancer is sufficient to increase the CD44+/CD24lo stem cell pool, resulting in increased sphere forming capacity in vitro, as well as elevated tumorigenicity and metastasis in vivo." (PMID 34459003, 2021). "CUL4A demonstrated the potential to promote (epithelial-)mesenchymal transition through the activation of ZEB1 in breast cancer cells." (PMID 34359668, 2021). "miR-141 binds to the 3′UTR of its downstream target gene ZEB1, suppresses the VM formation ability of breast cancer cells." (PMID 33542193, 2021). "Recently, we found that ELF3 is highly expressed in the luminal subtype of breast cancer cells, and represses upregulation of ZEB1/2 by ETS1 in such cells." (PMID 33712555, 2021). "This is, to our knowledge, the first report linking B3GALT5 to EMT and β-catenin/ZEB1 axis in breast cancer." (PMID 33413566, 2021). "Among DUBs, ubiquitin specific peptidase 51 (USP51) binds to the N-terminal of ZEB1 and increases ZEB1 protein stability in breast cancer cell lines." (PMID 33808323, 2021). "Not surprisingly, OSM has also been shown to induce EMP by regulating the Lin28/Let7/HMGA2 and miR200/Zeb1 circuits via STAT3 in breast cancer, leading to the initiation and maintenance of an EMP program both in vitro and in vivo." (PMID 34361105, 2021). "Recent studies have reported that ZEB1 can also induce breast cancer resistance to radiotherapy 37, which is also an important reason for the resistance of tumor cells to chemotherapy." (PMID 33391437, 2021). "It is already a well-established fact that the BCL6 promotes EMT by the Zinc finger E-box binding homeobox 1 (ZEB1)-mediated transcriptional repression of E-cadherin in breast cancer cells." (PMID 33806361, 2021). "USP51 has been demonstrated as a deubiquitinase of ZEB1 in breast cancer cells, and its catalytic activity is induced by phosphorylation of CDK4/6." (PMID 34575114, 2021). "Unsurprisingly, however, the low expression level of the miR-200 family in breast cancer enhances ZEB1/ZEB2 transcriptions, inducing TGF-β/BMP signalling to sustain EMT." (PMID 34868979, 2021).